IFNG (interferon gamma)
Diseases named in the same sentence as IFNG in open-access papers (continued):
Sharing a sentence is not in itself a finding about the gene and the disease.
tumor (continued). "In particular, authors observed an improvement in cytotoxic T cells’ activation and interferon gamma (IFNγ) production under CD276 signal regulation, while a tumor escaping from immune cell surveillance was also identified by activating NFAT, NF-kB, and AP-1-related molecular pathways." (PMID 36555714, 2022). "IFNγ ELISpots were used to quantify the CD8+ T cell functional response to the different tumor targets in the presence or absence of tumor-produced CCN4 protein." (PMID 35418177, 2022). "Interferon gamma (IFN-γ) secreted by CD8+ cytotoxic T cells promotes lipid peroxidation and ferroptosis by inhibiting the expression of SLC3A2 and SLC7A11, two subunits of system xc− in tumor cells." (PMID 36552652, 2022). "We find that A2BAR antagonists rescue T and NK cell proliferation, IFNγ and perforin production, and increase tumor infiltrating lymphocytes infiltration into tumor spheroids without altering the expression of adhesion molecules." (PMID 35580926, 2022). "We do not know, however, whether the TAMs need to directly receive the IFNγ signal and, if this were the case, whether both events need to occur on the same TAM or, on the contrary, they could happen on different TAMs of the tumor microenvironment." (PMID 35903540, 2022). "Increased IFNγ secretion by NK cells primed with VMAPRTLFL was observed in controls and patients compared with unstimulated and control peptide-stimulated cells in the presence of UM-SCC-2A target cells or of primary tumor cells." (PMID 36341402, 2022). "Of note, IFNγ can spread long distances (several hundred microns) acting on tumor cells not expressing the antigen with the potential to promote antigen spread and the generation of tumor-specific T-cell responses." (PMID 36189315, 2022). "While high tumor mutation burden is associated with better immunotherapy response through the generation of neoantigens that establish tumor “foreignness” to the immune system, CD8 T-cell recognition of these neoantigens requires tumor MHC-I expression and intact IFNγ signaling." (PMID 36230753, 2022). "In the tumor microenvironment (TME), the role of CD8+ T cells can be enhanced by cancer immunotherapy, in turn, immunotherapy-activated CD8+ T cells release cytokines including interferon γ (IFNγ)." (PMID 36349201, 2022). "Conversely, one of the other major effects of IFNγ is upregulation of major histocompatibility class-I (MHC-I) gene expression and therefore in the setting of cancer, increased tumor antigen processing and presentation leading to improved T-cell recognition and cytotoxicity." (PMID 35459800, 2022). "Furthermore, IFNγ and radiotherapy synergistically repress SLC7A11 expression, further enhancing lipid oxidation and ferroptosis in tumor cells." (PMID 34826064, 2022). "Molecular mechanism related studies showed that although the NK cells gathered at the tumor site, they were prevented from killing tumor cells by eADO and A2AR hindering the nutritional, promoting and cytolytic activities of NK cells, and finally inhibiting the production of IFNG." (PMID 36518306, 2022). "Anti-DDR1-ECD monoclonal antibody resulted in fewer and shorter arrangements of collagen fibers at the tumor edge, which enhanced immune cell infiltration, increased the total number of infiltrating CD8+ and CD4+ T cells, and promoted interferon gamma (IFN-γ) production." (PMID 35935941, 2022). "Tissue-resident memory T (TRM) cells are tumor antigen-reactive TILs that produce a magnitude of cytotoxic mediators, such as granzyme B and perforin, as well as cytokines, such as interferon-gamma (IFN-γ) and tumor necrosis factor (TNF), in the tumor microenvironment (TME)." (PMID 35663939, 2022). "To verify if IFNγ was directly involved in TFF1 silencing, we used the recombinant cytokine on KATO III, a tumour cell line that expresses high levels of the gastrointestinal protein, and confirmed that the treatment with the pro-inflammatory cytokine reduces both mRNA and protein levels of TFF1." (PMID 36514982, 2022).
tumor (continued). "However, compared with second generation CAR, third generation CAR increased cytokine secretion (IFNγ), maintained a low exhausted phenotype and enhanced CAR T-cell tumor infiltration in mouse model." (PMID 35729339, 2022). "In chronic immune responses and tumors, interferon-gamma (IFN-γ) produced by T cells induces the expression of PD-L1 at the antigen-presenting cells and tumor cells followed by down-regulation of the immune responses, which eventually yield to the failure of immunostimulants." (PMID 35656179, 2022). "Accordingly, a low dose of recombinant IFNγ strongly upregulated PD-L1 in tumor cells, irrespective of the presence of TGFβ or SMAD4." (PMID 35155243, 2022). "We also confirmed that IFNγ was required for killing of the tumor cells, as we observed no antitumor cytotoxicity upon IFNγ blockade in the transwell assays." (PMID 33976133, 2021). "Biomarkers predictive of the immunotherapeutic effects of ICIs have been extensively studied and discussed, with their predictive efficacy thought to depend on tumor antigenicity and antigen-presentation efficiency as measured by APS, IIS, TIS, CD8, IFNγ, IFNγ.GS, PDL1, TIDE, and APS7." (PMID 33495404, 2021). "Indeed, MSI tumors are known for being highly intruded by tumor-infiltrating lymphocytes (TILs) such as CD8+ cytotoxic lymphocytes, Th1-activated cells that produce IFNγ, and CD45 RO+ T memory cells." (PMID 33916641, 2021). "IFNγ and TNF-family cytokines have been reported to maintain the anti-tumor subtype of TANs." (PMID 34386431, 2021). "CXCL16 enhances IFNγ production by NKT cells, while IL-12 enhances IFNγ secretion by iNKT cells, NK cells, Th1 CD4+ and CD8+ T cells, providing a positive feedback loop to support a robust anti-tumor immune response." (PMID 34680322, 2021). "In addition, IL-4 was detected at low levels and IFNγ was undetected in both paired MPE and mesothelioma tumor supernatant in another study." (PMID 33987104, 2021). "Upon recognition of the antigen, the expanded T cells produced IFNγ and TNFα and specifically killed antigen-positive cells in vitro with high efficacy, sparing antigen-negative tumor cells." (PMID 33796916, 2021). "In addition, interferon-gamma can recruit macrophages and cytotoxic CD8 + T cells or directly inhibit the proliferation of Th2 cells, thereby exerting effective anti-tumor effects." (PMID 34699318, 2021). "Tumour cell-derived galectins have been shown to impair the activities of IFNγ-induced chemokines, CXCL9/10/11 by decorating ECM glycans and subsequently trapping intra-tumoural IFNγ." (PMID 33401460, 2021). "However, DLBCL clusters that correlated with tumor-conditioned monocytes highly expressed CD64, CD36, and S100A9 and thus presented similarities with IFNγ in-vitro polarized macrophages." (PMID 34975843, 2021). "The increase of tumor-infiltrating and IFNγ-secreting CD4+ and CD8+ T cells, and the elevation of key Th-1 and CTL (cytotoxic T lymphocyte)-driving cytokines IFNγ and IL-12, together reveals that IP-001 favors the initiation of cytotoxic T lymphocytes with T-helper type 1 response." (PMID 33668932, 2021). "Moreover, IFNγ released by CD8+ T cells inhibits expression of SLC3A2 and SLC7A11 on tumor cells, leading to tumor ferroptosis." (PMID 33801234, 2021). "Inhibiting IFNγ signaling in low/absent MHC-I tumors stimulated the production of IFNγ by exhausted T cells, which drove the maturation of innate immune cells to kill tumor cells." (PMID 34853298, 2021). "After stimulation, the percentage of C02-Activated-IFNG and C06-Activated-IL2RA of TCR-TMART-1 was downregulated, while the fragment of C01-Activated-CD69, C11-Activated-IL15, and C12-Cytotoxic-GNLY was upregulated with increased tumor PD-L1 levels." (PMID 33754038, 2021).
tumor (continued). "Consistently with the increased proportion of MDMs expressing M1 markers, we observed that the co-culture of murlentamab-opsonized SKOV3-R2+ tumor cells with both M0 and TAM-like MDMs induced a significant increase in IL1β, IL6 and IFNγ pro-inflammatory cytokine production." (PMID 33924378, 2021). "CD4+ T cells primarily mediate anti-tumour immunity by providing help for CD8+ CTL and antibody responses, as well as via secretion of effector cytokines such as interferon-γ (IFNγ) and tumour necrosis factor-α (TNFα), and, under specific contexts, via direct cytotoxicity against tumour cells." (PMID 32457487, 2021). "Tumor CD200 expression was correlated with significantly decreased tumor infiltration from CD4-positive and CD8-positive T cells and decreased production of IFNγ and TNFα." (PMID 33804482, 2021). "The PDO TILs activities were evaluated by treatment with anti-PD-1 or anti-PD-L1 in murine tumor organoids that showed a strong increase of CD8 TILs and T cell activation markers such as interferon-gamma (IFNγ), perforin-1 (PRF1), and granzyme B recapitulating the PD-1/PD-L1 immune checkpoint." (PMID 34074330, 2021). "Notably, glucose modification not only greatly increased the tumor-specific killing of CD8+ T cells, but also promoted the infiltration of TNFα- and IFNγ-producing CD8+ T cells in TEM." (PMID 34794428, 2021). "Interestingly, inhibition of the histone H3K27 methyltransferase enhancer of zeste homolog 2 (EZH2) activity in Tregs induces Treg-mediated pro-inflammatory functions, enhancing IFNγ production by CD8+ and CD4+ Th1 cells and anti-tumor immune responses." (PMID 33801234, 2021). "The increased IFNG response together with IL4, IL10, VEGF, TGF-beta and immune checkpoints comprise the tumor microenvironment that dominating the immune response, making artificial manipulation of one component only transiently alter the equilibrium reached by such biological response network." (PMID 34566988, 2021). "IFNγ upregulates IDO on MSCs, and blocking of IDO completely abolishes the protective effect of MSCs on HCC cells, suggesting that IDO plays an important role in the stromal cell mediated immune suppression seen in the tumor microenvironment." (PMID 34869307, 2021). "In vitro exposure of unpolarized (M0) bone-marrow-derived macrophages (BMDM) from control EMT6 tumor-bearing mice to IFNγ and TNFα induced significant M1 but not M2 polarization." (PMID 34446712, 2021). "IFNγ is required for the expression of human major histocompatibility complex (MHC) class I and class II proteins, and therefore, plays a critical role in tumor immunogenicity." (PMID 34901003, 2021). "Mass cytometry analysis identified 20 separate T cell subsets, with proliferating activated CD8 T cells expressing IFNγ and GrzB to be expanded prior to tumor growth regression, indicating that a dominant and functional CD8 response is important for tumor immunity after PD-1 blockade." (PMID 34912335, 2021). "In addition to IFNγ, Ling and colleagues also reported elevated IL-17A production by MAIT cells in both the periphery and tumours of patients with CRC." (PMID 33808058, 2021). "Furthermore, administration of tirabrutinib to the KrasG12D orthotopic mouse model reduced tumor cell growth and infiltrating regulatory B cells with increasing numbers of CD8+IFNγ+ T cells, thus also indicating BTK’s role in immune function." (PMID 34063667, 2021). "Also, the role of peptides in IFNγ expression induction seems important due to the fact that IFN plays a significant role in tissue homeostasis, immune and inflammatory responses and tumor immunosurveillance." (PMID 33466712, 2021). "Indeed, GL261-MGH and CT2A tumor cells upregulated both MHC I and II in response to IFNγ stimulation in vitro in a dose-dependent manner." (PMID 33976133, 2021).
tumor (continued). "In tumor microenvironment, gCpG treatment increased Th1 and CTL infiltration, increased M1 macrophages, decreased Tregs and MDSCs populations, and promoted inflammatory milieu with enhanced secretion of IFNγ and TNFα." (PMID 34794428, 2021). "By analyzing the gene expression profiles of these TCGA tumor samples using GSEA with respect to high vs. low NAMPT expression, we observed an increase in both pro-inflammatory (including IFNγ response genes), and pro-glycolytic signatures correlating with higher NAMPT expression." (PMID 33976173, 2021). "Additionally, IL-15 in a HCC animal model promotes tumor control, based on the long-term expansion of tumor-specific CD8 T cells, increasing IFNγ secretion and cytotoxicity, and also decreasing the expression of co-inhibitory molecules on dendritic cells." (PMID 33923463, 2021). "CXCR3+ T cells and NK cells recruited to the TME by IL-18 and IP-10/CXCL10 are unlikely to possess anti-tumor function, although they are active in IFNγ production." (PMID 33718235, 2021). "In contrast to the GZMB+ CAR T cells, the more delocalized expression of IFNγ may indicate that these CAR T cells migrate in and out from the area of the tumor surface more frequently or express IFNγ for an extended period of time post-antigen exposure." (PMID 34155235, 2021). "Thus, IFNγ released by Nrp1−/− Tregs results in increased fragility of other populations of intratumoral Tregs, increasing anti-PD1-driven anti-tumor immune responses." (PMID 33801234, 2021). "While i.t. injection of TNFα or IFNγ alone did not induce significant apoptosis in LLC tumours, co-treatment with TNFα and IFNγ induced whole tumour cell apoptosis to 24%." (PMID 34285232, 2021). "Increased MHCII pathway expression, then, likely reflects ENT‐induced changes in tumor expression profiles as well as changes in tumor cell biology that in turn promote CD8 T cell activation, subsequent increases in IFNγ production, and resultant upregulation of antigen presentation." (PMID 33369199, 2021). "In cultured LLC cells and MMTV-PyMT tumour cells, AKTi addition led to a reduction of cell viability by 37% and 35%, respectively, regardless of the inclusion of TNFα and/or IFNγ." (PMID 34285232, 2021). "The cytolytic activity of TCR-TMART-1 was inhibited by increasing the percentage of tumor cells expressing PD-L1, affecting the secretion of Granzymes and pro-inflammatory cytokines in Tnull and TCR-TMART-1, including TNFα, IFNγ, and IL2." (PMID 33754038, 2021). "Furthermore, treatment with SFV/IFNg inhibited CD11b+ cell infiltration and decreased the CD206+ and CD38+ cell populations, explaining the observed inhibition of tumor growth." (PMID 34835178, 2021). "Moreover, CD4+ Th1 T-lymphocytes destroy tumor cells also trhough the secretion of cytokines and chemokines, especially interleukin 2 (IL2) and interferon-gamma (IFNγ), which help the recruitment of further NK cells, CD8+ T-lymphocytes and macrophages." (PMID 33920423, 2021). "Overall, as only TILs with high level of recognition were used, the mean percentage of “bulk” TILs that were reactive to autologous tumor cells was high (measured with upregulation of CD137, TNF, IFNγ or CD107a: 41% in CD8+ TILs, n=21; and 29% in CD4+ TILs, n=16." (PMID 34707600, 2021). "Further support for the immunostimulatory role of IL-10 comes from studies in rodent tumour models where IL-10 administration promotes proliferation and expansion of tumor-resident cytotoxic CD8+ T cells as well as IFNγ production, thereby enhancing antitumor activity." (PMID 34234779, 2021). "High salt treatment enhanced the secretion of inflammatory cytokines (IFNγ, TNFα and IL-17) from DLNs, tumor splenocytes and non-tumor splenocytes, as compared to respective equimolar mannitol treatment." (PMID 33918403, 2021). "Patients exhibited increases in circulating iNKT cell numbers and IFNγ production, but few patients showed any reduction in tumor progression, indicating the treatment was not effective." (PMID 34680322, 2021).
tumor (continued). "IL-32 may promote CD8+ T cell IFNγ expression that enhances the antitumor activity, but at the same time induce CD4+ T cell Foxp3 expression, which could suppress tumor immune response." (PMID 34414188, 2021). "Other cytokines (CCL2, IFNγ, IL-12, IL-10, TNFα, IL-4, and IL-1β) evaluated were not significantly changed, suggesting that additional unidentified tumor-derived soluble factors promote alternative activation in BMDMs." (PMID 35008514, 2021). "Whole-tissue tile scans of the CD19, CAR RNA FISH co-staining with either GZMB RNA FISH (n = 5) or IFNγ RNA FISH (n = 5) also indicated that the highest expression of GZMB but not IFNγ is in close proximity to the tumor." (PMID 34155235, 2021). "Various tumor entities with elevated immune response have dense CD8 pos T cell infiltrates in common, which are responsible for a local production of interferon gamma (IFNγ)." (PMID 34743724, 2021). "In addition, A2AR targeting with CRISPR/Cas9 resulted in almost complete resistance to NECA-mediated suppression of IFNγ and TNF production upon coculture with Her2-positive tumor cells." (PMID 34050151, 2021). "CD8+ T cells, especially IFNγ+ CD8+ T cells, are considered major drivers of anti-tumor immunity, and IFNγ could enhance the activation of naive T cells in the tumor." (PMID 34880875, 2021). "CD40L induced CD86 and CD83 expression on DC but in this small study of only 26 patients, CD40L did not improve anti-tumor specific T cell proliferation, IFNγ ELISPOT response, DTH response or relapse free survival." (PMID 33854509, 2021). "We and others have shown that a short-term stimulation through IL12, IL15, and IL18 receptors induce NK cells with an enhanced ability to produce IFNγ, TNF, and MIP1α in response to cytokines, activating receptors triggering or restimulation with tumor targets." (PMID 34187852, 2021). "In this study, compared with other groups, more CD3+ and CD8+ T cells expressing IFNγ were determined in tumors of D-Nap-GFFY-T317 (TH)-treated group, indicating more T lymphocytes and CTLs infiltrating into tumor microenvironment with activated IFNγ expression." (PMID 33456564, 2021). "Although all fucoidans led to a significantly higher release of IFNγ in PBMCs, these activating effects did not translate into an increase in tumor cell apoptosis and reduction of tumor cell proliferation, at least under the first three tested concentrations." (PMID 35049864, 2021). "Most tumors in the presence of inflammation and IFNγ will express MHC class II, if citrullinated peptides are then generated in response to stress or autophagy these can then be loaded onto MHC class II for presentation on the surface of tumor cells." (PMID 33859638, 2021). "CCL2 may enhance the phagocytotic ability of tumor-entrained macrophages and initiate the subsequent release of cell-death-related molecules such as RANTES, MIF, CXCL-12, and IFNγ." (PMID 34386431, 2021). "Various subpopulations of the tumor-infiltrating T cells express the TRM marker CD103, possibly reacting with E-cadherin expressed by cancer cells and residing in the tumor, and the expression of CD103 correlates with the cytotoxic function of these T cells with the production of IFNγ and granzymes." (PMID 34884736, 2021). "MHC-I expression is frequently low or negative on tumor cell lines but upregulated rapidly in response to IFNγ." (PMID 34201655, 2021). "In accordance with scRNA-seq data, the Oxali + anti–PD-L1 combo increased the percentage and/or total numbers of tumor-infiltrating CD8+ and CD4+ T cells, CD107+IFNγ+ CTLs, IFNγ+ CD8+, and TNF+IFNγ+ CD8+ T cells, CD8+CD44+ Teff cells, and CD8+CD44+PD1+TIM-3+ T cells analyzed by flow cytometry." (PMID 33602823, 2021). "For instance, upregulation of IFNγ in CD8+ T cells in co-culture was independent of tumor cell STING signaling, occurring in both WT and STING KO cells." (PMID 33995649, 2021).